DCLK1 (doublecortin like kinase 1)
Diseases named in the same sentence as DCLK1 in open-access papers (continued):
Sharing a sentence is not in itself a finding about the gene and the disease.
tumor (continued). "Given the functional attributes of Doublecortin-like kinase 1 (DCLK1) in tumor growth, invasion, metastasis, cell motility, and tumor stemness, it is emerging as a therapeutic target in gastrointestinal cancers." (PMID 34445192, 2021). "Our study anew established the functional role of Dclk1+ tumor cells for the maintenance and expansion of primary and metastatic PDAC and its precursor lesions in vivo." (PMID 33393460, 2021). "Recently, DCLK1 has been identified as a novel, tumor-specific stem cell marker in the intestine and pancreas." (PMID 33762936, 2021). "This study clearly demonstrated for the first time the pivotal stem cell activity of Dclk1+ tumor cells for the maintenance and expansion of primary PDAC and its precursor lesions as well as metastatic lesions in vivo." (PMID 33393460, 2021). "Further radiobiological studies are required to highlight the role of DCLK1 and its downstream signaling pathway with radiosensitivity of other tumor cell lines." (PMID 34268251, 2021). "Within GI tumors, DCLK1 is strongly correlated with an EMT phenotype and tumor immune suppressive infiltrates including tumor-associated macrophages, M2 macrophages, and T regulatory cells." (PMID 34830884, 2021). "And it is reported that DCLK1 not only upregulates in tumor cells but also scattered in the intestinal epithelium where the lower crypts in normal murine and human intestines are most frequently observed, heightening concern about toxicity." (PMID 33613769, 2021). "Histologically, passaged tumors were also indistinguishable from primary subcutaneous tumors and original PDACs, and a very small number of Dclk1+ tumor cells were observed in those tumors." (PMID 33393460, 2021). "We found that tumor DCLK1 expression correlated with immune score in COAD and STAD (Pearson r = 0.63, p < 0.0001 and Pearson r = 0.4, p < 0.0001, respectively), and stromal score (Pearson r = 0.85, p < 0.0001 and Pearson r = 0.76, p < 0.0001, respectively)." (PMID 31979136, 2020). "Herein we review key advances in the understanding of DCLK1 and DCLK1+ TCs function in the context of the tumor and immune microenvironment and discuss future directions for DCLK1-based research and development." (PMID 33348546, 2020). "Emerging data concerning targeting DCLK1 with small molecular inhibitors, monoclonal antibodies, and chimeric antigen receptor T-cells shows promising effects on inhibiting tumor growth and regulating the tumor immune microenvironment." (PMID 33348546, 2020). "Another key area of focus for DCLK1′s role in the tumor microenvironment involves its basic activity in cell signal transduction." (PMID 33348546, 2020). "The normal mucosa as reference, set to 100 and the tumour tissue for DCLK1 563.11 ± 166.84 and LGR5 722.40 ± 215.94 (mean ± SEM) respectively, Mann–Whitney test, P < 0.001." (PMID 32814764, 2020). "DCLK1 promotes tumor initiation and metastasis formation in different tumor entities including breast, CRC, and pancreas." (PMID 32756469, 2020). "It is important for us to emphasize that unlike traditional extracellular antigens that are upregulated in tumors but undetectable in normal tissues, DCLK1 is highly upregulated in tumor cells and expressed at low levels in normal tissues." (PMID 31878090, 2019). "The downregulation of DCLK1 upregulates several tumor suppressor miRNAs, including let-7a, thus inhibiting tumor growth, metastasis, and angiogenesis." (PMID 31757094, 2019). "A compelling study published in Nature Genetics utilizing the Dclk1CreErt2 mouse model demonstrated that Dclk1 specifically marks TSCs that continuously produce tumor progeny in the polyps of ApcMin/+ mice." (PMID 31878090, 2019). "Tumor-bearing mice were given intravenous (i.v.) injections of DCLK1 CAR-T or mock CAR-T cells (1 × 107 cells/mice/dose) every week for three weeks (days 7, 14, and 21 post-cell implantations)." (PMID 31878090, 2019).
tumor (continued). "We found higher expression of DCLK1 in most of the tumor samples and assessed the effect of DCLK1 expression on patient survival." (PMID 31467540, 2019). "Recently it has been found that miR-137 acts as a tumor suppressor in colorectal cancer via suppression of uncontrolled cell proliferation by DCLK1 downregulation." (PMID 31530793, 2019). "Mice treated with CBT-511 had a significant reduction in tumor size compared to those given mock CAR-T treatments (mean tumor volume of mock CAR-T versus DCLK1 CAR-T = 2123 versus 1216 mm3 with a p = 0.02)." (PMID 31878090, 2019). "Hyperplasia, BE metaplasia and tumour development have been found to be accompanied by expansion of Dclk1+ cells “ ”." (PMID 31348796, 2019). "Doublecortin-like kinase 1 (DCLK1) is a microtubule-associated kinase that regulates EMT and is associated with microRNAs known to regulate tumor growth and progression." (PMID 31878090, 2019). "Expression level of DCLK1 was closely correlated to tumor differentiation, lymph node invasion and clinical phase of the patients." (PMID 29246000, 2017). "Ten studies investigated the expressions of DCLK1 in different degree of tumor differentiation, including 1411 cases of well and moderate differentiation and 389 cases of poor differentiation." (PMID 29246000, 2017). "We also found that tumours formed by GR cells had obviously increased staining of DCLK1 compared with their GS parental cell." (PMID 28244691, 2017). "We also studied the expression of Dclk1 that marks Tuft cells in the normal intestine and was recently suggested to be a tumor stem cell marker in the intestine." (PMID 27811361, 2016). "It is reported that DCLK1 regulates tumor cell self-renewal by controlling the expression of pluripotency factors." (PMID 27335684, 2016). "Taken together, our results suggest that DCLK1 serum levels and DCLK1 positive circulating tumor cells should be further assessed for their potential diagnostic and prognostic significance." (PMID 25723399, 2015). "In human PDAC tissue, DCLK1 immunostaining indicated that DCLK1 expression was higher in the stromal cells than that in tumor epithelial cells, suggesting a potential conversion to mesenchymal cells during the early tumorigenic process." (PMID 25723399, 2015). "We found that approximately 52% of YFP+ cells in the blood of KPCY mice are Dclk1+, suggesting that a large portion of circulating tumor cells are Dclk1+ cells." (PMID 25723399, 2015). "We observed during our studies that Huh7 cells-derived tumor growth can be inhibited in a murine model by administering Poly Lactic-co-Glycolic Acid (PLGA) nanoparticles (NPs) encapsulated anti-DCLK1 siRNAs inhibited (communicated elsewhere)." (PMID 25948779, 2015). "Doublecortin-like kinase 1 protein (Dclk1) is a marker of gastrointestinal tuft cells and has been suggested to mark quiescent stem cells and tumor-initiating stem cells (TSCs)." (PMID 26362399, 2015). "Mean tumor expression of DCLK1 protein was 2 fold higher in tumors compared to normal kidney (data not shown)." (PMID 25605241, 2015). "The invasive front of the tumor was clearly marked by the presence of DCLK1-positive cells in the mucosal layer." (PMID 26622789, 2015). "In resected surgical tissues, DCLK1 expression intensity in the stromal cells was significantly higher than that observed in tumor epithelial cells." (PMID 25723399, 2015). "We observed a significant (p < 0.01) upregulation of let-7a pri-miRNA (>2.5-fold) in tumors treated with NP-siDCLK1 compared with control and NP-siSCR-treated tumors, indicating that DCLK1 knockdown induces miRNA let-7a in tumor xenografts." (PMID 26468984, 2015). "More than 50% of circulating YFP+ tumor cells are positive for Dclk1, suggesting that DCLK1+ tumor cells are among the cells undergoing EMT." (PMID 25723399, 2015).
tumor (continued). "Here, we employed transcriptome analysis, RNA interference, tumor xenografts, patient's liver tissues and hepatospheroids to investigate DCLK1-regulated inflammation and tumorigenesis in the liver." (PMID 25948779, 2015). "Based on earlier reports that DCLK1 negatively regulates tumor suppressor miRNAs post-transcriptionally, we performed luciferase reporter gene-based assays." (PMID 26468984, 2015). "Researchers demonstrated that Dclk1 marks TSCs that continuously produce tumor progeny in the intestinal polyps of ApcMin/+ mice, and suggested that Dclk1 marks the cell of origin in an ApcMin/+ model of intestinal tumorigenesis." (PMID 26468984, 2015). "Prior to malignant transformation, DCLK1 expression in tissue and plasma makes expression sensitive for conversion from normal to pre-neoplasia, considerably limiting its specificity." (PMID 26468984, 2015). "On the basis of these findings, DCLK1 was believed to play a fundamental role in tumor cells, including NET cells, where neuroendocrine markers are positive-for promoting cell migration, proliferation and tumorigenesis." (PMID 26622789, 2015). "We have recently reported that expression of Dclk1, a Tuft cell and tumor stem cell (TSC) marker, 24h after high dose total-body gamma-IR (TBI) can be used as a surrogate marker for crypt survival." (PMID 26270561, 2015). "Using these probes we performed single-linkage hierarchical clustering and found that DCLK1 has a unique methylation signature in RCC tumor tissue." (PMID 25605241, 2015). "We analyzed the expression of various tumor suppressor miRNAs (miR-144, miR-145, and miR-200a, b, c) that are regulated by DCLK1." (PMID 26468984, 2015). "The intensity of DCLK1 expression in stromal elements was stronger than that in the tumor epithelial cells." (PMID 25723399, 2015). "Numerous reports have established that DCLK1 regulates tumor suppressor miRNAs that play key roles in tumor initiation, progression, and metastasis." (PMID 26468984, 2015). "Therapeutic targeting of DCLK1 in gastrointestinal cancer is highly desirable because of its expansion in tumors and tumor stem cell status." (PMID 24885928, 2014). "Thus, we hypothesize that the increase in Dclk1 associated with the loss of Apc escalate cellular transformation and stem cell compartment to facilitate expansion of dysplasia and adenocarcinoma in tumor-initiated intestinal epithelium." (PMID 25211188, 2014). "In HCT116 (colon) and AsPC-1 (pancreatic) tumor xenografts, DCLK1 siRNA nanoparticle treatment significantly reduces tumor growth and inhibits pluripotency and angiogenic factors without any indication of toxicity." (PMID 24885928, 2014). "Quantitative analysis of tumor suppressor and tumor promoter miRNAs revealed most were at normal or near-normal levels after Dclk1-knockdown." (PMID 25211188, 2014). "Recent studies show that Dclk1 specifically marks tumor stem cells (TSCs) that self-renew and generate tumor progeny in ApcMin/+ mice." (PMID 25211188, 2014). "Earlier reports and the data presented above indicate that DCLK1 negatively regulates tumor suppressor miRNAs like let-7a, miR-144 and miR-200a." (PMID 24040120, 2013). "Here we demonstrate that the knockdown of DCLK1 using poly(lactide-co-glycolide)-encapsulated-DCLK1-siRNA results in AsPC1 tumor growth arrest." (PMID 24040120, 2013). "We conclude that DCLK1 plays a significant master regulatory role in pancreatic tumorigenesis through the regulation of multiple tumor suppressor miRNAs and their downstream pro-tumorigenic pathways." (PMID 24040120, 2013). "One of the most striking features of DCLK1 is its tumor-specific expression pattern." (PMID 40869256, 2025). "DCLK1 further regulates NF-κB signaling to limit pro-inflammatory (M1) activation while promoting macrophage recruitment and activation in a manner that supports both tissue repair and tumor progression." (PMID 40563698, 2025).
tumor (continued). "Given the functional response of D-peptide 1 on tumor growth, we identified potential pro-tumorigenic binding partners that have the potential to bind specifically to the C-terminal extracellular domain of DCLK1." (PMID 40162222, 2025). "DCLK1, enriched in radiation-resistant tuft cells, engages directly or indirectly in a network of stress-adaptive signaling pathways that promote epithelial regeneration, immune modulation, and tumor resistance." (PMID 40563698, 2025). "Moreover, DCLK1+ cells modulate the tumor microenvironment (TME) by skewing immune polarization (ILC2, M2 macrophages, myeloid-derived suppressor cells (MDSCs), regulatory T cells) and remodeling the extracellular matrix (ECM) via fibroblast crosstalk." (PMID 40563698, 2025). "Tumor-bearing mice were randomly assigned to either the DMSO or DCLK1-INT group (n = 8 per group)." (PMID 40775208, 2025). "Targeting DCLK1 may shift the immune landscape toward a pro-inflammatory, tumor-suppressive phenotype." (PMID 40563698, 2025). "Furthermore, research indicates that DCLK1 is essential for tumor progression, angiogenesis and epithelial-mesenchymal transition." (PMID 40963862, 2025). "Through IL13 and PDG2 secretion, and the DCLK1/Hippo interaction, TCs may influence the expression of these checkpoint molecules in the tumor microenvironment, and targeting them could help overcome TC-mediated immunomodulation." (PMID 38892399, 2024). "Notably, the RBE CTRL group displayed a significantly larger tumor size compared to the RBE DCLK1-KO group, indicating a substantial impairment in subcutaneous tumor development upon DCLK1 deactivation." (PMID 38980538, 2024). "In addition, they used DCLK1CreERT2/+; Rosa26R; ApcMin/+; Rosa26iDTR/+ mice to delete DCLK1+ cells, resulted in tumor regression." (PMID 38254219, 2024). "And DCLK1 might contribute to TAM-mediated inhibition of CD8+ T-cells to enhance tumour growth in the tumour microenvironment." (PMID 38062554, 2024). "Paraffin sections from tumor tissues were acquired, and DCLK1 expression was assessed through IHC." (PMID 38980538, 2024). "miR-206, a known tumor suppressor, was downregulated when DCLK1 was high." (PMID 38928187, 2024). "DCLK1 expression exhibited a notable upregulation in CCA samples compared to non-tumor tissues." (PMID 38980538, 2024). "Accumulating studies indicated that DCLK1 is related to tumour development." (PMID 38062554, 2024). "The average weight of tumor tissues treated by DCLK1-IN-1 or S31-201 was also lower." (PMID 37069669, 2023). "Therefore, the impacts of DCLK1 on anti-tumor immunity in TNBC were investigated by 4T1 syngeneic mouse model." (PMID 37069669, 2023). "Through controlling the Wnt/-catenin pathway, DCLK1 aids in the maintenance of tumor stem cells." (PMID 37443105, 2023). "All these data revealed the importance of targeting DCLK1 in evoking anti-tumor immunity." (PMID 37069669, 2023). "Therefore, we investigated the influence of DCLK1 on anti-tumor immunity by using 4T1 syngeneic mouse model." (PMID 37069669, 2023). "Moreover, in vivo results revealed that inhibition of DCLK1 increased the infiltration of CD8+ T cells, which suggested that DCLK1 inhibitor was conducive to alter immunologically cold tumor to immunologically hot tumor benefiting from immunotherapy." (PMID 37069669, 2023). "Tumor immune cell infiltration analysis by flow cytometry revealed that more cytotoxic T cells could be detected in DCLK1-knockout tumors and the deletion of CD8+ T cells could restore the growth of DCLK1-knockout tumors." (PMID 37069669, 2023). "Four days post-implantation, these tumor-bearing mice were randomly divided into three groups and treated with DCLK1-IN-1 via oral gavage (20 mg/kg, every other day), S31-201 intraperitoneally (5 mg/kg, three times a week) and the corresponding solvent, respectively." (PMID 37069669, 2023).
tumor (continued). "To investigate whether the anti-tumor effects depend on antitumor immunity, we detected the infiltration of CD8+ T cells in tumor tissues treated with DCLK1-IN-1 and the corresponding solvent." (PMID 37069669, 2023). "Importantly, it was found that, when treated with DCLK1 inhibitor, the tumour volumes of DCLK1‐overexpressing group were substantially decreased." (PMID 35522902, 2022). "Several studies have linked DCLK1 overexpression to clinicopathological characteristics and poor prognosis in CRC patients, indicating that it may play a role in tumor development." (PMID 35717205, 2022). "Whether it is the acquisition of DCLK1+ expression by tumour stem cells due to aberrant Wnt signaling (for example due to loss of APC) which leads to their ability to produce IL-25 remains to be explored." (PMID 36263033, 2022). "Moreover, in subcutaneous xenograft tumour models treated with 5‐fluorouracil or/and β‐catenin inhibitor, we found that the tumour volumes of DCLK1‐overexpressing group were substantially decreased." (PMID 35522902, 2022). "Besides, elevated levels of DCLK1 were closely correlated with poor outcomes and tumour recurrence and metastasis." (PMID 35522902, 2022). "DCLK1+ cells have been shown to induce tumor growth in the GI tract." (PMID 36704202, 2022). "Importantly, depletion of DCLK1+ tuft cells reduced tumour burden in models of CRC both in vitro and in vivo, indicating that these IL-25-expressing tuft cells can support intestinal tumorigenesis." (PMID 36263033, 2022). "DCLK1 functions as tumor inducer in gastric, stomach, intestine, pancreas, colon, breast, and lung." (PMID 36250024, 2022). "Moreover, tuft cells marker DCLK1 was especially expressed in intestinal tumor stem cells, whereas, it was hardly expressed in the colon steady stage." (PMID 35359953, 2022). "It has been reported that DCLK1 played an important role in promoting intestinal tumorigenesis, and depletion of DCLK1 reduced the stemness and inhibited progression of tumors, thus suggesting its role in regulating pro-survival signals and tumor cell pluripotency." (PMID 36569325, 2022). "Future studies would be required to uncover the essential role of Dclk1+ tumor/CSCs by specific lineage ablation and to determine whether targeting Dclk1+ tumor cells could be a novel therapeutic approach against PDAC." (PMID 33393460, 2021). "Similarly, it was found herein that A549 cells overexpressing DCLK1 can form larger and more tumor spheres in the same number of days, as compared with cells transfected with empty vector." (PMID 33762936, 2021). "In order to assess the effect of DCLK1-IN-1 on immune-mediated tumor cell killing, we pretreated 786-O cells with 5 or 10 μM of DCLK1-IN-1 for 48 h, selected live cells via trypan blue exclusion, which were stained with fluorescent dye Calcein-AM and seeded into a 96 well plate in equal numbers." (PMID 34830884, 2021). "Furthermore, we here performed for the first time the genetic lineage tracing with live imaging within primary PDAC and its precursor lesions as well as metastatic lesions that directly provided crucial stem cell activity of Dclk1+ tumor cells in vivo." (PMID 33393460, 2021). "There were very few Dclk1+ cells within EGFP+ PDAC tumor cells 14 days after tamoxifen injection." (PMID 33393460, 2021). "Using genetic lineage tracing with a dual-recombinase system and live imaging, we showed that Dclk1+ tumor cells continuously provided progeny cells within pancreatic intraepithelial neoplasia, primary and metastatic PDAC, and PDAC-derived spheroids in vivo and in vitro." (PMID 33393460, 2021). "In those spheroids, Dclk1 was expressed only in a small fraction of tumor cells." (PMID 33393460, 2021). "Furthermore, a thousand of Dclk1+ and Dclk1− tumor cells collected from primary subcutaneous tumors were re-transplanted into the flank of other NOD/SCID mice." (PMID 33393460, 2021).